PRR32 (proline rich 32)
Synonyms: CXorf64
Tractability: Antibody: the Human Protein Atlas places it where antibodies can reach.
Gene: Protein-coding gene on chromosome X (126,819,729 to 126,821,786, forward strand). Ensembl gene ENSG00000183631.
Subcellular location (Human Protein Atlas): Plasma membrane; Centrosome; Nuclear speckles
Gene Ontology:
Molecular function: protein binding
Homologues: Orthologues: chimpanzee PRR32 (99% identical), macaque PRR32 (90% identical), rabbit PRR32 (73% identical), pig PRR32 (63% identical), rat Prr32 (52% identical), mouse Prr32 (51% identical).
Diseases named in the same sentence as PRR32 in open-access papers:
PRR32 is named in the same sentence as 2 diseases in open-access papers, as found by Europe PMC text mining. Sharing a sentence is not in itself a finding about the gene and the disease.
PRR32 shares sentences with these, for which no sentence is quoted: cardiac ischemia (1 paper); congestive heart failure (1).